GALR1 (galanin receptor 1)
Description:
Receptor for the hormone galanin. The activity of this receptor is mediated by G proteins that inhibit adenylate cyclase activity.
Synonyms: GALNR; GALNR1
Tractability: Small molecule: a structure with a bound ligand is known; a high-quality ligand is known; it belongs to a druggable protein family. Antibody: UniProt places it where antibodies can reach, with high confidence; its Gene Ontology location is reachable by antibodies, with high confidence; UniProt predicts a signal peptide or a membrane-spanning region; the Human Protein Atlas places it where antibodies can reach. PROTAC: a small molecule that binds it is known.
Target class: Membrane receptor; Peptide receptor (family A GPCR); Family A G protein-coupled receptor; Galanin receptor; Short peptide receptor (family A GPCR)
Gene: Protein-coding gene on chromosome 18 (77,249,848 to 77,277,900, forward strand). Ensembl gene ENSG00000166573.
Subcellular location: Cell membrane
Subcellular location (Human Protein Atlas): Plasma membrane
Pathways (Reactome):
Signal Transduction: G alpha (i) signalling events; Peptide ligand-binding receptors
Gene Ontology:
Molecular function: galanin receptor activity; peptide hormone binding; protein binding; G protein-coupled receptor activity; neuropeptide binding
Biological process: positive regulation of cortisol secretion; positive regulation of transcription by RNA polymerase II; negative regulation of adenylate cyclase activity; neuropeptide signaling pathway; adenylate cyclase-activating G protein-coupled receptor signaling pathway; G protein-coupled receptor signaling pathway; positive regulation of cytosolic calcium ion concentration
Cellular component: plasma membrane; membrane
Genetic constraint (gnomAD): Loss-of-function variants: 8 observed, 14.68 expected, observed/expected ratio (o/e) 0.54, 90% interval 0.32 to 0.98. The upper end of that interval is the gene's LOEUF score, 0.98, which puts it in group 4 of 6, group 1 being the genes least tolerant of losing a copy. Missense variants: 416 observed, 432.35 expected, observed/expected ratio (o/e) 0.96, 90% interval 0.89 to 1.04. Synonymous variants: 199 observed, 199.32 expected, observed/expected ratio (o/e) 1, 90% interval 0.89 to 1.12.
Homologues: Orthologues: chimpanzee GALR1 (99% identical), macaque GALR1 (99% identical), pig GALR1 (93% identical), mouse Galr1 (92% identical), dog GALR1 (91% identical), rat Galr1 (91% identical), guinea pig GALR1 (88% identical), tropical clawed frog galr1 (81% identical), zebrafish galr1a (70% identical). Paralogues in human: GALR3 (34% identical), HCRTR2 (30% identical), HCRTR1 (29% identical), NPFFR1 (29% identical), NPFFR2 (29% identical), QRFPR (28% identical), CCKAR (26% identical), CCKBR (25% identical), FFAR4 (25% identical), AVPR1A (23% identical), AVPR2 (21% identical), OXTR (21% identical), and 4 more.
Diseases named in the same sentence as GALR1 in open-access papers:
GALR1 is named in the same sentence as 90 diseases in open-access papers, as found by Europe PMC text mining. Sharing a sentence is not in itself a finding about the gene and the disease. The quoted sentences say what the papers report.
depression (18 papers, 2012 to 2026). "The higher relevance of the GalR2, GalR3 and GalR1 gene polymorphisms in stress-induced depression and the galanin system-independent effects of the currently used antidepressants suggest that novel antidepressants acting on GalR1-3 could be developed." (PMID 30627087, 2018). "GAL, upon its action on its three GAL receptors (GALR1-3), participates in numerous physiological processes and different disease, including mood regulation and depression in animal models." (PMID 34639188, 2021). "The present results, based on the rat PPD depression model, provide evidence for involvement of GALR1 in the PFC in depression-like behavior." (PMID 30487761, 2018). "Treatment of GALR1-siRNA in PCF reversed depression-like behavior accompanied with the reversion of down-regulated CREB-BDNF and 5-HT levels." (PMID 30487761, 2018). "Taken together, galanin receptors GalR1 and GalR2 play a differential role in regulation of depression-like behavior." (PMID 30627087, 2018). "Our recent study has also shown that the increased expression of GalR1 in the ventral periaqueductal gray of chronic mild stress rats is related to depression-like behavior." (PMID 30487761, 2018). "Depression-like behaviors seem to be induced by the activation of GALR1 and attenuated depression-like behaviors derived by the activation of GALR3." (PMID 23986909, 2013). "Behavioral and neurochemical studies support a role of galanin and NPY in mood disorders and GalR1-3 and NPYY1 receptors have been the receptors implicated in depression with GalR subtype specific antagonists and NPYY1 agonists having an antidepressant role." (PMID 23112793, 2012). "It is possible that in depression this antagonistic allosteric mechanism in the GalR1-5-HT1A heteroreceptor complexes is dysfunctional which may lead to disturbances in their operation in meso-limbic 5-HT neurotransmission." (PMID 28270751, 2017). "One possibility is that GalR1-expressing neurons in the vHC may inappropriately enhance attention towards negative events thereby promoting behaviors with strong affective components such as anxiety and depression." (PMID 39131306, 2025). "In the present study, lower level of 5-HT in PPD model rats and ameliorated depression-like behavior together with reversed 5-HT level after GALR1-siRNA treatment suggesting that antidepressant effect of GALR1-siRNA might be mediated by reversing downregulation of 5-HT in PFC." (PMID 30487761, 2018). "Therefore, known GalR antagonists may have multiple targets and it would be of high interest to develop an antagonist for treatment of depression that selectively target the GalR1–GalR2 heteromer postulated to be the galanin N-terminal fragment receptor." (PMID 23112793, 2012). "Activation of GALR1 and GALR3 induces depression-like behaviors, whereas activation of GALR2 inhibits depressive-like behaviors." (PMID 40048451, 2025). "In this article we, in part, focus on the role of the 5-HT2A-D2R and putative GalR1-GalR2-5-HT1AR heterocomplexes in mental disease, with a particular focus on major depression." (PMID 34440670, 2021). "It is not known which of the 5-HT1A heteroreceptor complexes plays a leading role in reducing depression: 5-HT1A–FGFR1, 5-HT1A–5-HT2A, GalR–5-HT1A, or GalR1–GalR2–5-HT1A heteroreceptor complexes." (PMID 29865267, 2018). "In addition, we explored whether or not there was a causal link between change of GALR1 expression and depression-like behaviors in PPD model rats and possible signaling mechanisms involved." (PMID 30487761, 2018). "GALR1 is highly expressed in PFC, and GALR1 mRNA level was significant increase in PFC of major depression patients." (PMID 30487761, 2018). "Heterobivalent drugs with GalR1 and GalR2 antagonist pharmacophors may specifically target the GalR1 and GalR2 binding pockets of the GalR1-GalR2 heteroreceptor complex, disrupt their function and represent a new strategy for treatment of depression and anxiety." (PMID 28270751, 2017).
depression (continued). "A recent alternative hypothesis suggests that depression results from alterations in receptor activity due to formation of homoreceptor and heteroreceptor complexes involving receptor types including 5HT1A, 5HT7, galR1, and fibroblast growth factor receptor 1 (FGFR1)." (PMID 29375372, 2017). "GalR1 and GalR2 are expressed throughout the brain,while GalR3 is confined to the hypothalamus It has been postulated that the dysregulation of the normal interaction between NE and Gal in the amygdala may contribute to stress-related disorders, such as depression, anxiety and PTSD." (PMID 27907151, 2016). "Neuromodulation of neuronal networks in depression via 5-HT, galanin peptides and zinc involve a number of GPCR heteroreceptor complexes in the raphe-hippocampal system: GalR1-5-HT1A, GalR1-5-HT1A-GPR39, GalR1-GalR2, and putative GalR1-GalR2-5-HT1A heteroreceptor complexes." (PMID 28270751, 2017).
Anxiety (10 papers, 2006 to 2025). Intense feelings of nervousness, tension, or panic often arise in response to interpersonal stresses. "Feeding, learning and memory, seizures, pain, anxiety, and mood problems have all been linked to the GALR1 gene (OMIM#600377), which may explain the behavioral problem of our patient; however, the implications of this gene’s hemizygosity remain unknown." (PMID 37296475, 2023). "This neuropeptide is involved in numerous physiological and behavioral functions, including learning and memory, neuroendocrine control, gastrointestinal motility, feeding and anxiety, through the actions of three receptors (GalR1-3)." (PMID 27907151, 2016). "The three galanin receptor subtypes, GALR1, GALR2, and GALR3, are widely distributed in mood-related brain areas such as hypothalamus, central amygdaloid nucleus, and thalamus and may mediate anxiety-associated behavior." (PMID 16623937, 2006). "It will also be important to know whether GalR1-GalR2-5-HT1A heterocomplexes exist in the amygdala and other brain regions known to participate in the modulation of anxiety." (PMID 35681521, 2022).
colorectal cancer (5 papers, 2015 to 2022). A primary or metastatic malignant neoplasm that affects the colon or rectum. "The expression of GALR1 has been reported to be associated with survival in colorectal cancer, and its inactivation by methylation has been associated with survival in head and neck cancer." (PMID 25950620, 2015). "GAL and its receptor GalR1 might have novel potential for overcoming chemotherapy resistance though mitogen-activated protein kinase signaling and the insulin signaling pathway in colorectal cancer." (PMID 35751103, 2022).
epilepsy (5 papers, 2012 to 2023). A brain disorder characterized by episodes of abnormally increased neuronal discharge resulting in transient episodes of sensory or motor neurological dysfunction, or psychic dysfunction. "GALR1 belongs to the galanin neuropeptide family; galanin has been studied in Alzheimer’s disease, epilepsy, and memory consolidation studies and is known for its potential role in learning and memory." (PMID 38254919, 2023). "Some studies has also reported that GalR1-KO mice exhibit spontaneous epilepsy although other studies could not replicate this phenotype." (PMID 23233848, 2012). "Interestingly, the predicted targets of cluster 5 include the gamma-aminobutyric acid B receptor 2 (Gabbra2), the galanin receptor 1 (GalR1) and the glutamate receptor ionotropic AMPA 2 (Gria2), all genes whose products are implicated in the regulation of excitability and in epilepsy." (PMID 26382856, 2015). "Galmic is a non-peptide agonist with higher affinity for GalR1 compared to GalR2, which under conditions of intrahippocampal administration was 6-fold more potent than galnon in inhibiting self-sustaining status epilepticus (SE), an in vivo model for epilepsy." (PMID 23233848, 2012).
endometrial cancer (4 papers, 2015 to 2022). Primary or metastatic malignant neoplasm involving the endometrium (mucous membrane that lines the endometrial cavity). "They found that methylation of GALR1 promoter region is one of the most common molecular alterations in endometrial cancer, and it predicted the presence of endometrial malignancy with a specificity of 78.9% and a sensitivity of 92.7%." (PMID 26251921, 2015). "Furthermore, DNA methylation of GALR1 is the most frequent epigenetic change in endometrial cancer, and the detection of GALR1 methylation in vaginal swabs can accurately identify female endometriosis and malignant changes." (PMID 33150179, 2020).
glioblastoma (4 papers, 2019 to 2022). The most malignant astrocytic tumor (WHO grade IV). "In contrast to OPRM1 mRNA, GalR1 mRNA encoding for the galanin receptor 1 is abundant in most glioblastoma specimens (second box plot)." (PMID 32560384, 2020). "Among the relevant candidate genes involved in tumor progression, GALR1 encodes galanin receptor 1 (GALR1), which is most likely responsible for the GAL binding observed in glioblastomas, idicating its influence on GBM differentiation and growth." (PMID 31537867, 2019).
glioma (4 papers, 2019 to 2022). A benign or malignant brain and spinal cord tumor that arises from glial cells (astrocytes, oligodendrocytes, ependymal cells). "Functional analysis of the DEGs showed that GALR1 and GRM5 of neuroactive ligand-receptor interactions signaling pathways may be relaed to malignant progression of gliomas." (PMID 31537867, 2019).
head and neck squamous cell carcinoma (4 papers, 2018 to 2023). A squamous cell carcinoma that arises from any of the following anatomic sites: lip and oral cavity, nasal cavity, paranasal sinuses, pharynx, larynx, and salivary glands. "Recently, GALR1 was also suggested as a tumor suppressor gene that was frequently silenced in head and neck squamous cell carcinoma; moreover, galanin and GALR1 were reported to inhibit human oral cancer cell proliferation." (PMID 29462183, 2018). "GALR1 has been intensively studied in head and neck squamous cell carcinoma (HNSCC)." (PMID 33150179, 2020). "In addition, GALR1 is a candidate tumor suppressor that is frequently silenced in head and neck squamous cell carcinoma (HNSCC)." (PMID 29462183, 2018). "Galanin (GAL) stimulates a variety of signal transduction and integration pathways by activating its receptors GALR1, GALR2, and GALR3,14, 15 and thus far, GALRs have been found to be the most effective markers for predicting the prognosis of head and neck squamous cell carcinoma (HNSCC) patients." (PMID 36039037, 2023).
colitis (3 papers, 2016 to 2024). Inflammation of the colon. "Interestingly, in the previous study we have observed a significant decrease in the expression of galanin, GalR1, GalR2 and GalR3 receptors (in the mucosa, tunica muscularis and lymphocytes) in the porcine descending colon wall affected by dysentery associated colitis." (PMID 27175780, 2016). "Namely, decreased GALR1 expression was observed in Brachyspira hyodysenteriae-induced colitis in pigs." (PMID 38632282, 2024).
non-small cell lung carcinoma (3 papers, 2016 to 2020). A group of at least three distinct histological types of lung cancer, including non-small cell squamous cell carcinoma, adenocarcinoma, and large cell carcinoma. "GALR1 has also been used in the formation of a risk model to diagnose non-small-cell lung cancer (NSCLC)." (PMID 33150179, 2020).
oral cancer (3 papers, 2017 to 2021). "Galanin and GALR1 inhibited human oral cancer cell proliferation by down-regulating cyclin D1 and activating cyclin-dependent kinase inhibitors." (PMID 29462183, 2018). "In oral cancers, GALR1 promoter hypermethylation significantly and inversely correlates with DFS time." (PMID 29100314, 2017).
status epilepticus (3 papers, 2010 to 2024). Status epilepticus is defined as a continuous seizure lasting more than 30 min, or two or more seizures without full recovery of consciousness between any of them. "This variability in the degree of brain damage following systemic KA administration is in agreement with previous studies and confirms previous observations that GalR1 gene disruption renders the brain more susceptible to status epilepticus-induced brain damage." (PMID 21179451, 2010). "In the present study, we report that reduction of GalR1 mRNA via null mutation or injection of the GalR1 antagonist, galantide, prior to kainate-induced status epilepticus induces hippocampal damage in a mouse strain known to be highly resistant to kainate-induced neuronal injury." (PMID 21179451, 2010).
breast carcinoma (2 papers, 2015 to 2023). "Meanwhile, GALR1 has also been a subtype determining gene in breast cancer, which suggests its potentially powerful role in cancer diagnosis." (PMID 25657825, 2015).
cholestasis (2 papers, 2023 to 2026). Impairment of the bile flow caused by obstruction within the liver, or outside the liver in the bile duct system. "GalR1 was also found, and although there were modest increases in galR1 expression in pCCA patients with cholestasis, significance was not reached." (PMID 41546485, 2026).
colon cancer (2 papers, 2023 to 2024). "While GALR1 and TLX1 showed near perfect performance in classifying colon cancer (AUC of 0.97 for both), ZNF154 only achieved an AUC of 0.81 within this tumor type." (PMID 37835520, 2023).
gastric cancer (2 papers, 2020 to 2023). A primary or metastatic malignant neoplasm involving the stomach. "By contrast, ZNF154 displayed the largest amount of differential methylation for stomach cancer (difference in median methylation 0.63), improving performance over TLX1 or GALR1 (difference in median beta value at 0.50 and 0.30, respectively)." (PMID 37835520, 2023).
head and neck cancer (2 papers, 2015 to 2021). A primary or metastatic malignant neoplasm affecting the head and neck. "Promoter hypermethylation of the GALR1 gene was associated with a decrease in disease-free survival of head and neck cancer patients and its potential use as a biomarker for prognosis was suggested." (PMID 34207933, 2021).
Insulin resistance (2 papers, 2016 to 2025). Increased resistance towards insulin, that is, diminished effectiveness of insulin in reducing blood glucose levels. "The HAMD/HAMA/FF scores showed significant correlations with several factors such as PGE, CRP, GAL, GALR1, insulin resistance, and PAI1 levels." (PMID 40048451, 2025). "Nonetheless, more studies are needed using GalR1 specific antagonists and GalR1 mutant mice to further explore the effect of central GalR1 on amelioration of insulin resistance." (PMID 27127795, 2016). "The present findings showed that the beneficial effect of central M617 on insulin sensitivity was same as that of central GAL in adipose tissues, suggesting that the mitigatory effect of central GAL on insulin resistance is mainly mediated by activation of GalR1." (PMID 27127795, 2016). "The results suggest that activation of GalR1 in brain may inhibit CRP secretion to ameliorate insulin resistance." (PMID 27127795, 2016). "Our current results indicated that the CRP levels were markedly decreased by central administration of M617, suggesting that activation of GalR1 in brain might reduce CRP discharge to ameliorate insulin resistance." (PMID 27127795, 2016).
ischemic stroke (2 papers, 2017 to 2022). A stroke disorder caused by obstruction of blood flow to the brain, due to thrombotic (local blood clot formation) or embolic (due to a blood clot or other material traveling from another site) event. "Activation of galanin receptor 1 (GalR1) has an anti-apoptotic effect in ischemic stroke." (PMID 36505409, 2022). "However, the link between GalR1, cPKCγ, and the downstream mechanisms, which regulate this neuroprotection in ischemic stroke injury, remains to be explored." (PMID 28203483, 2017). "Meanwhile, after 24 h of reperfusion, both GAL and GalR1 showed a significant increase in the ipsilateral versus contralateral cortex, suggesting GAL’s involvement in ischemic stroke." (PMID 28203483, 2017).
melanoma (2 papers, 2012 to 2022). A malignant, usually aggressive tumor composed of atypical, neoplastic melanocytes. "The first known galanin receptor, galanin receptor type 1 (GalR1), was isolated from the Bowes human melanoma cell line and subsequently rat and mouse receptor was cloned." (PMID 23233848, 2012).
Obesity (2 papers, 2022 to 2025). Accumulation of substantial excess body fat. "Notably, cinchonine, a natural compound, exerted simultaneous inhibitory effects on these pathways (i.e., it significantly downregulated gene expression of Srepbf1, Galr1, and Galr2 in fat tissue), resulting in reduced adipogenesis and mitigated obesity." (PMID 39968178, 2025). "Another research revealed that galanin could regulate the pain threshold in obesity by central galanin receptor-1 and peripheral galanin receptor-2, though the antinociceptive effect of activating the receptors had not been clearly characterized." (PMID 36082069, 2022).